DOCK1 (dedicator of cytokinesis 1)
Description:
Involved in cytoskeletal rearrangements required for phagocytosis of apoptotic cells and cell motility. Along with DOCK1, mediates CRK/CRKL regulation of epithelial and endothelial cell spreading and migration on type IV collagen. Functions as a guanine nucleotide exchange factor (GEF), which activates Rac Rho small GTPases by exchanging bound GDP for free GTP. Its GEF activity may be enhanced by ELMO1.
Synonyms: DOCK180; ced5
Tractability: Small molecule: it has a high-quality binding pocket. Antibody: its Gene Ontology location is reachable by antibodies, with medium confidence; the Human Protein Atlas places it where antibodies can reach. PROTAC: ubiquitination databases record sites on it.
Gene: Protein-coding gene on chromosome 10 (126,905,397 to 127,452,518, forward strand). Ensembl gene ENSG00000150760.
Subcellular location: Cytoplasm; Membrane
Subcellular location (Human Protein Atlas): Cytosol; Nucleoplasm; Actin filaments; Focal adhesion sites; Nucleoli; Plasma membrane
Pathways (Reactome):
Signal Transduction: PTK6 Regulates RHO GTPases, RAS GTPase and MAP kinases; RAC1 GTPase cycle; RAC2 GTPase cycle; RHOG GTPase cycle; VEGFA-VEGFR2 Pathway
Cell-Cell communication: SRC activates STAT3 in a quantitative manner, through Cadherin-11 (CDH11), RAC1 and gp130 (IL6ST)
Developmental Biology: DCC mediated attractive signaling
Disease: FCGR3A-mediated phagocytosis
Hemostasis: Factors involved in megakaryocyte development and platelet production
Immune System: Regulation of actin dynamics for phagocytic cup formation
Gene Ontology:
Molecular function: guanyl-nucleotide exchange factor activity; protein binding; small GTPase binding
Biological process: positive regulation of epithelial cell migration; positive regulation of substrate adhesion-dependent cell spreading; regulation of postsynapse assembly; apoptotic process; cell migration; integrin-mediated signaling pathway; myoblast fusion; phagocytosis, engulfment; signal transduction; small GTPase-mediated signal transduction
Cellular component: cytoplasm; glutamatergic synapse; guanyl-nucleotide exchange factor complex; postsynapse; cytosol; plasma membrane; membrane
Genetic constraint (gnomAD): Loss-of-function variants: 126 observed, 229.46 expected, observed/expected ratio (o/e) 0.55, 90% interval 0.47 to 0.64. The upper end of that interval is the gene's LOEUF score, 0.64, which puts it in group 2 of 6, group 1 being the genes least tolerant of losing a copy. Missense variants: 1,829 observed, 2,267.9 expected, observed/expected ratio (o/e) 0.81, 90% interval 0.77 to 0.84. Synonymous variants: 843 observed, 828.68 expected, observed/expected ratio (o/e) 1.02, 90% interval 0.96 to 1.08.
Homologues: Orthologues: chimpanzee DOCK1 (98% identical), dog DOCK1 (98% identical), guinea pig DOCK1 (97% identical), rat Dock1 (97% identical), rabbit DOCK1 (96% identical), macaque DOCK1 (96% identical), mouse Dock1 (95% identical), pig DOCK1 (92% identical), tropical clawed frog dock1 (86% identical), zebrafish dock1 (73% identical), Caenorhabditis elegans ced-5 (28% identical). Paralogues in human: DOCK5 (65% identical), DOCK2 (59% identical), DOCK3 (38% identical), DOCK4 (37% identical), DOCK11 (17% identical), DOCK10 (17% identical), DOCK6 (17% identical), DOCK9 (17% identical), DOCK7 (16% identical), DOCK8 (16% identical).
Diseases named in the same sentence as DOCK1 in open-access papers:
DOCK1 is named in the same sentence as 53 diseases in open-access papers, as found by Europe PMC text mining. Sharing a sentence is not in itself a finding about the gene and the disease. The quoted sentences say what the papers report.
breast carcinoma (29 papers, 2013 to 2026). "The present study aimed to elucidate the underlying mechanisms of DOCK1-regulated metastasis in claudin-low breast cancer (CLBC)." (PMID 31717460, 2019). "More importantly, a high level of DOCK1 expression is associated with poor prognosis in patients with basal-like breast cancer and ovarian cancer, which suggests an operative machinery by DOCK1 in the tumorigenesis and metastasis of TNBC." (PMID 31717460, 2019). "The overexpression of DOCK1 has been observed in various malignancies, including thyroid, bladder, and breast cancers." (PMID 37894381, 2023). "DOCK1–Rac signaling as an HER2 effector pathway is essential for HER2‐mediated breast cancer progression to metastasis." (PMID 36597889, 2023). "We identify circDOCK1-1 generated from the DOCK1 gene as an important regulator of the epithelial differentiation of mammary tumour cells." (PMID 34771489, 2021). "In current research, we examined the relative expression levels of miR-486-5p and Dock-1 in 80 pairs of breast cancer tissues and corresponding adjacent normal tissues, also the effects of modifying their levels in cultured cells." (PMID 31528235, 2019). "Dock1 overexpression reversed the effect caused by the overexpression of miR-486-5p.The current research offers new perception into metastasis and invasion of breast cancer cells and therefore may contribute to the progress of novel strategies against breast cancer." (PMID 31528235, 2019). "To identify the roles of Dock1 in IL-22-induced breast cancer cells invasion, we conducted a Transwell invasion assay." (PMID 31528235, 2019). "Interference with DOCK1 expression by shRNA resulted in re-expression of claudin-1 in conjunction with significant inhibition of cell viability and motility of claudin-low breast cancer cells." (PMID 31717460, 2019). "MiR-486-5p directly bound the Dock1 mRNA 3' untranslated region and inhibited IL-22-induced EMT of breast cancer cells via the Dock1/NF-κB/Snail signaling pathway." (PMID 31528235, 2019). "Dock1 protein expression was markedly increased in most of the breast cancer tissues compared with corresponding ANTs." (PMID 31528235, 2019). "Alternatively, the Rac1 GEFs P-Rex1, Vav2/3, and Dock1 have been shown to contribute to metastatic behavior in particular breast cancer subtypes." (PMID 29769144, 2018). "For example, the Rac1 GEFs P-Rex1 and Vav2/3 contribute to metastasis in luminal subtype breast cancers, while the Rac1 GEF Dock1 controls metastasis in HER2-positive breast cancers." (PMID 29769144, 2018). "As a prototype member in DOCK family, DOCK1 is involved in migration and invasion of various cancer cells including breast cancer, ovarian cancer and glioblastoma multiforme." (PMID 29069784, 2017). "DOCK1 gene expression carries prognostic significance in breast cancer, ovarian cancer and glioblastoma multiforme through activation of c-JUN, STAT3, and Rac1." (PMID 29069784, 2017). "One example is the circular isoform of DOCK1, whose linear isoform encodes a “dedicator of cytokinesis”, a RacGEF, and was the most highly expressed circular isoform in MCF-7, a breast cancer cell line." (PMID 24039610, 2013). "Our findings that m6A methylation of DOCK1-derived circRNA is increased in TNBC compared to luminal subtypes align with evidence that DOCK1 promotes aggressive breast cancer behavior through its regulation of cell motility, invasion, and epithelial–mesenchymal transition (EMT)." (PMID 41516402, 2026). "For example, ErbB2 (HER2) interacts with DOCK1 in breast cancer cells." (PMID 40105697, 2025). "Interestingly, accumulating reported evidence indicates that DOCK1 is a key oncogene that drives tumorigenesis by mediating cell migration and metastasis, such as liver cancer and breast cancer." (PMID 38570856, 2024). "Moreover, previous studies revealed that DOCK1 promotes tumor proliferation and invasion in glioma and breast cancer." (PMID 35217990, 2022).
breast carcinoma (continued). "Moreover, in a HER2+ breast cancer mouse model, DOCK1 promoted invasion to the lungs, where the lung metastases overexpressed DOCK1 compared to primary tumors." (PMID 32322580, 2020). "Hence, the results manifested that Dock1 increased mesenchymal properties of breast cancer cells and triggered EMT under stimulation of IL-22." (PMID 31528235, 2019). "In current study, we determined the role of miR-486-5p, Dock1, and IL-22 in breast cancer EMT." (PMID 31528235, 2019). "DOCK1 is highly expressed in malignant breast cancer cells, especially in TNBC." (PMID 31717460, 2019). "Furthermore, RRP1B mediated DOCK1 depletion, which up-regulated claudin-1 expression, cell viability, and motility in claudin-low breast cancer cells." (PMID 31717460, 2019). "In addition, another report found that Dock1 (Dock 180) promotes heregulin-mediated Rac activation, which is essential for breast cancer growth and metastasis." (PMID 27999268, 2016). "The ELMO1, DOCK1, and RAC1 pathway has been implicated in: phagocytosis of Gram-negative bacteria by macrophages, T cell migration in primary lymphocytes, and actin cytoskeleton regulation during breast cancer metastasis." (PMID 25901943, 2015). "We discovered that the number of metastatic tumor nodules in lung of mice was lower in the group with overexpression of miR-486-5p or downregulation of Dock1 under stimulation with IL-22, suggesting miR-486-5p could repress breast cancer cells metastasis in mice models." (PMID 31528235, 2019). "To explore the potential function of miR-486-5p and Dock1 in genesis and progression of breast cancer, we detected the level of miR-486-5p using qRT-PCR and the level of Dock1 using immunohistochemistry and western blot in 80 pairs archived frozen breast cancer tissues and ANTs." (PMID 31528235, 2019). "In summary, our study demonstrated that IL-22 and Dock1 promoted the invasion, metastasis, and EMT of breast cancer cells." (PMID 31528235, 2019). "We first investigated the correlation between the DOCK1 transcript level and the probability of survival of TNBC patients using the dataset from the Kaplan–Meier Plotter (Breast Cancer)." (PMID 31717460, 2019). "This study found that Dock1 played important part on invasion, metastasis and EMT of breast cancer, which is consistent with previous findings." (PMID 31528235, 2019). "We illustrated that IL-22 and Dock1 promote the invasion, metastasis, and EMT of breast cancer using Transwell invasion assay, western blot and immunofluorescence." (PMID 31528235, 2019). "In breast cancer cells, Gas6/Axl signaling also leads to rac activation and invasion through the scaffold protein Elmo and the RHO-GTPase activator DOCK1." (PMID 26356564, 2015). "The tumor differentiation, lymphatic and distant metastasis, and the levels of E-cadherin and Vimentin were correlated with upregulation of Dock1 in breast cancer, but age, tumor size, or hormonal level were not." (PMID 31528235, 2019). "The results showed that ribosomal RNA processing protein 1B (RRP1B), a metastatic modulator in breast cancer, exhibited the most changes (up to 15-fold) after a three day-knockdown of DOCK1 in BT-549 cells (data not shown)." (PMID 31717460, 2019). "Moreover, DOCK1 mediates EGFRvIII stimulation in glioblastoma tumorigenesis, as well as in HER2-accelerated breast cancer progression." (PMID 31717460, 2019). "IL-22 did not affect Dock1 protein levels in breast cancer cells." (PMID 31528235, 2019). "This study demonstrated that DOCK1 mediates growth and motility through down-regulated claudin-1 expression via the RRP1B–DNMT–claudin-1 pathway and that claudin-1 serves as an important effector in DOCK1-mediated cancer progression and metastasis in claudin-low breast cancer cells." (PMID 31717460, 2019).
glioma (17 papers, 2010 to 2025). A benign or malignant brain and spinal cord tumor that arises from glial cells (astrocytes, oligodendrocytes, ependymal cells). "Platelet derived growth factor receptor α (PDGFRα) facilitated the malignant biological behavior of glioma by promoting protein kinase A-dependent serine phosphorylation of DOCK1." (PMID 38438882, 2024). "A molecular complex, functioning as a GEF for Rac, including engulfment and cell motility 1 (ELMO1) and dedicator of cytokinesis 1 (Dock180) (ELMO1/Dock180) has been identified as a key player in migration and invasion of glioma cells." (PMID 35011682, 2021). "Since miR-31 is hypermethylated in glioma, Dock1 is overexpressed, leading to IL-8 induced mesenchymal transition." (PMID 32906592, 2020). "Dock1 has a significant effect on chemotaxis and migratory potential of cancer cells including glioma." (PMID 32906592, 2020). "The stimulation of PDGFRα by PDGF growth factor leads to the phosphorylation of DOCK1 which, in turn, activates Rac1 and subsequently enhances glioma cell migration and invasion." (PMID 32089990, 2020). "Overexpression of miR-31 in vivo results in Dock1 downregulation followed by reduced invasion of glioma cells." (PMID 32906592, 2020). "On the other hand, dedicator of cytokinesis 1 (DOCK1), also known as DOCK180, is a Rac GEF which associates with cofactor engulfment and cell motility 1 (ELMO1) overexpressed in glioma cells and activates Rac1." (PMID 32089990, 2020). "Our previous study also showed that Dock1 acts vial part in the IL8-triggered EMT of glioma cells." (PMID 31528235, 2019). "Importantly, ELMO1, by forming the complex with dedicator of cytokinesis 180 (Dock180), serves as a Rac1 guanine nucleotide exchange factor that stimulates glioma cell migration and invasion." (PMID 22494416, 2012). "In glioma, DOCK1 and engulfment and cell motility 1 (ELMO1) were reported to promote human glioma cell invasion." (PMID 38415469, 2025). "It modulates Dock1 expression, while Dock1 promotes the IL8-induced chemotaxis and mesenchymal transition of glioma cells through the NF-jB/Snail signaling pathway." (PMID 34199293, 2021).
acute myeloid leukemia (8 papers, 2016 to 2023). Acute myeloid leukemia (AML) is a group of neoplasms arising from precursor cells committed to the myeloid cell-line differentiation. "DOCK1 overexpression is closely associated with poor prognosis in acute myeloid leukemia." (PMID 36597889, 2023). "On the contrary, SETDB1 inhibits the expression of genes associated with acute myeloid leukemia (AML), such as Dock1, Hoxa9, and Six1, to delay MLL-AF9-mediated disease progression by promoting the differentiation of leukemia cells." (PMID 38057834, 2023). "This study aimed to explore the role of LINC00665, miR-4458 and DOCK1 and their interactions in the development of acute myeloid leukemia (AML)." (PMID 33658535, 2021). "In summary, our study concluded that the overexpression of DOCK1 as an unfavorable prognostic marker in acute myeloid leukemia possibly through its correlation with stemness, cell proliferation, motility and chemotaxis." (PMID 29069784, 2017). "It has been demonstrated that DOCK1 had adverse prognostic effect in acute myeloid leukemia (AML)." (PMID 31762818, 2019). "LINC00665 has been shown to be up-regulated in acute myeloid leukemia (AML) cells parallel with the increase in expression of Dedicator Of Cytokinesis 1 (DOCK1) and decrease in expression of miR-4458." (PMID 36429005, 2022). "SETDB1 functions as a tumor suppressor in Acute Myeloid Leukemia (AML) by promoter histone methylation and repression of tumorigenic genes, such as Sineoculis homeobox homolog 1 (Six1), HoxA9 and Dedicator of Cytokinesis 1 (Dock1)." (PMID 34440561, 2021).
ovarian carcinoma (7 papers, 2014 to 2024). A malignant neoplasm originating from the surface ovarian epithelium. "DOCK1 regulates cell motility and migration and has been implicated in ovarian cancer tumorigenesis." (PMID 25315765, 2014). "It was reported that DOCK1 expression was upregulated in ovarian cancer cells in contrast to that in normal ovarian epithelial cells." (PMID 38438882, 2024). "ELMO1 could help DOCK1 to regulate the migration ability of ovarian cancer cells." (PMID 38438882, 2024).
colorectal cancer (6 papers, 2021 to 2024). A primary or metastatic malignant neoplasm that affects the colon or rectum. "CircRNA dedicator of cytokinesis 1 (circ_DOCK1) is involved in colorectal cancer progression, but the mechanism underlying this circRNA that takes part in colorectal cancer development remains largely undetermined." (PMID 33685455, 2021). "And it was inversely associated with circ_DOCK1 level in colorectal cancer." (PMID 33685455, 2021). "For example, circRNA dedicator of cytokinesis 1 (circDOCK1), a circRNA first described in colorectal cancer, was detected a lower expression level in IA tissues compared with middle meningeal artery tissues by real-time PCR." (PMID 35359572, 2022). "Our study evaluated the oncogenic function of circ_DOCK1 on colorectal cancer development, and we firstly confirmed the circ_DOCK1/miR-132-3p/USP11 axis." (PMID 33685455, 2021). "In conclusion, our study displayed that circ_DOCK1 was upregulated in colorectal cancer, and circ_DOCK1 knockdown repressed growth and metastasis, and promoted apoptosis of colorectal cancer cells, possibly via increasing miR-132-3p and decreasing USP11." (PMID 33685455, 2021). "Circ_DOCK1 interference suppressed cell growth and metastasis, and increased apoptosis of colorectal cancer via decreasing USP11 by increasing miR-132-3p." (PMID 33685455, 2021). "Next, we explored additional regulatory network except for circ_DOCK1/miR-138/TERT/PD-L1 axis in colorectal cancer." (PMID 33685455, 2021). "And it was inversely associated with miR-132-3p level, but positively related to circ_DOCK1 level in colorectal cancer." (PMID 33685455, 2021). "By detecting circ_DOCK1 expression in 42 paired tumor and normal tissues, results showed circ_DOCK1 (hsa_circ_0020397) level was significantly increased in colorectal cancer tissues compared with normal samples, while hsa_circ_0020394 level was not obviously changed in tumor and normal samples." (PMID 33685455, 2021). "Furthermore, higher level of circ_DOCK1 was displayed in colorectal cancer cell lines (HCT116 and SW480) than human normal colonic epithelial cell line FHC cells." (PMID 33685455, 2021). "In this research, the purposes were to investigate the function of circ_DOCK1 (hsa_circ_0020397) on cell growth, metastasis, and apoptosis in colorectal cancer, and to explore whether it required the circ_DOCK1/miR-132-3p/USP11 network." (PMID 33685455, 2021). "In this way, the circ_DOCK1/miR-132-3p/USP11 axis participated in colorectal cancer development." (PMID 33685455, 2021). "Circ_DOCK1 expression was enhanced in colorectal cancer tissues and cells." (PMID 33685455, 2021). "Multiple isoforms of circ_DOCK1 have been reported to play important roles in colorectal cancer." (PMID 33685455, 2021). "Likewise, we also validated the anti-cancer function of this miRNA and found that circ_DOCK1 could regulate colorectal cancer progression by sponging miR-132-3p." (PMID 33685455, 2021). "Hence, we hypothesized the circ_DOCK1/miR-132-3p/USP11 axis might be an important network for circ_DOCK1 in colorectal cancer." (PMID 33685455, 2021). "Multiple evidences have reported that circ_DOCK1 could facilitate cell proliferation and constrain apoptosis in various cancers, like thyroid cancer, oral squamous cell carcinoma, bladder cancer, and colorectal cancer." (PMID 34109173, 2021). "Here, we focused on the circ_DOCK1 (hsa_circ_0020397) isoform, and confirmed circ_DOCK1 knockdown could repress cell growth and metastasis, and promoted apoptosis in colorectal cancer, which suggested circ_DOCK1 might function as an important target for colorectal cancer treatment." (PMID 33685455, 2021). "The specific expression and mechanism of circ_DOCK1 in colorectal cancer and bladder cancer have been reported, but there is no literature regarding the effect of circ_DOCK1 in cervical cancer." (PMID 38536591, 2024).
glioblastoma (6 papers, 2012 to 2024). The most malignant astrocytic tumor (WHO grade IV). "Dock1 (DOCK180), a GEF for Rac, becomes tyrosine phosphorylated by Src downstream of PDGFRα activation in glioblastoma cells." (PMID 23152932, 2012).
bladder cancer (4 papers, 2019 to 2024). "Subsequent studies found that downregulation of DOCK1 could increase the chemosensitivity in bladder cancer cells through preventing epithelial–mesenchymal transition." (PMID 36597889, 2023).